BGN (biglycan)
Diseases named in the same sentence as BGN in open-access papers (continued):
Sharing a sentence is not in itself a finding about the gene and the disease.
COVID-19 (2 papers, 2023 to 2024). A disease caused by infection with severe acute respiratory syndrome coronavirus 2. "This study aims to investigate the predictive potential of serum biomarkers, specifically decorin and biglycan, in assessing the severity and mortality risk among COVID-19 patients." (PMID 39906348, 2024). "In severe COVID-19 cases, abnormal ECM remodeling has been associated with pulmonary inflammation and fibrosis, suggesting a potential role for decorin and biglycan in these pathological processes." (PMID 39906348, 2024). "Serum decorin and biglycan levels are valuable biomarkers for predicting severity and mortality in COVID-19 patients." (PMID 39906348, 2024). "Another major finding of our study demonstrates that serum biglycan levels are significantly elevated in severe COVID-19 patients compared to healthy controls." (PMID 39906348, 2024). "The fundamental goal of this investigation is to determine the level of biglycan and decorin in COVID-19 patients (with moderate and severe symptoms) as compared to the control group." (PMID 39906348, 2024). "The levels of decorin and biglycan were measured across three groups: controls, patients with moderate COVID-19, and patients with severe COVID-19, with results expressed as mean ± SEM." (PMID 39906348, 2024). "Conclusively, our has found that severe COVID-19 patients had significantly lower serum decorin levels and higher biglycan levels compared to healthy controls." (PMID 39906348, 2024). "Previously, in an investigation, it was found that the expression of the biglycan gene increases notably in COVID-19 cases after more than 7 days of ventilator management." (PMID 39906348, 2024). "We also observed an increased biglycan gene expression in COVID-19 cases with more than 7 days of VM." (PMID 37964271, 2023). "Conversely, biglycan levels showed an increasing trend, being 66.15 ± 2.22 pg/mL in the control group, 70.02 ± 1.57 pg/mL in moderate COVID-19 patients, and 75.88 ± 1.97 pg/mL in severe COVID-19 patients, with an ANOVA p value of 0.0042." (PMID 39906348, 2024).
degenerative disc disease (2 papers, 2014 to 2019). "IVD degeneration has been found to spontaneously occur in biglycan-deficient (Bgn−/0) mice, which therefore represent a valuable in vivo model to study degenerative disc disease." (PMID 25293819, 2014). "Our studies, performed by 7TMRI assessment and histological evaluation, confirmed that IVD of Bgn−/0 mice were in a more advanced degenerative state than those of WT mice at every age examined, and thus, the biglycan deficiency significantly accelerated disc degeneration." (PMID 25293819, 2014).
dissection (2 papers, 2014 to 2023). The separation and isolation of tissues for surgical purposes, or for the analysis or study of their structures. "The CS side chains of the CSPG Biglycan can control elastin assembly in vascular walls, and targeted disruption of biglycan leads to abnormal collagen fibrils and aortic dissection and rupture." (PMID 24667694, 2014).
dystocia (2 papers, 2012 to 2021). Slow or difficult obstetric labor or childbirth. "Knockout of both DCN and BGN in mice was associated with a heightened risk of dystocia and delayed labor onset, which may be underreported in EDS women due to their widespread prevalence and easy treatment." (PMID 34638928, 2021). "Thus, the loss of both decorin alleles increases the risk of dystocia during labor despite the presence of both biglycan alleles." (PMID 22253749, 2012). "Thus, the biglycan/decorin double knockout mouse is a novel model of a genetic pathway for dystocia and delayed labor onset, which will be a useful model to test therapeutics and potentially decrease the rate of Cesarean births secondary to dystocia." (PMID 22253749, 2012).
heart failure (2 papers, 2020 to 2021). Inability of the heart to pump blood at an adequate rate to meet tissue metabolic requirements. "Several ECM proteins detected in this study have already been proposed as potential markers of heart failure, including osteoglycan (mimecan), fibulin-3, biglycan, and asporin." (PMID 33670142, 2021). "For example, decorin and biglycan become highly expressed in models of hypertrophy and heart failure and are responsible for facilitating fibrillogenesis and fibrosis." (PMID 32805183, 2020).
Hyperinsulinemia (2 papers, 2012 to 2020). An increased concentration of insulin in the blood. "We demonstrate here in the JCR:LA-cp rat that in the prediabetic milieu, aortic biglycan protein core content also increases significantly with age and correlates linearly with increasing hyperinsulinemia." (PMID 23316299, 2012).
Insulin resistance (2 papers, 2016 to 2020). Increased resistance towards insulin, that is, diminished effectiveness of insulin in reducing blood glucose levels. "The biglycan mRNA level is strongly associated with several parameters related to indices for body adiposity and insulin resistance; however, the association with the latter disappears after adjusting for BMI." (PMID 27465988, 2016). "Adipose tissue biglycan mRNA positively correlated with adiposity indices and insulin resistance parameters; however, this relationship disappeared after adjusting for BMI." (PMID 27465988, 2016). "The expression level of biglycan mRNA in adipose tissues, especially in VAT, showed remarkably strong positive correlations with parameters related to insulin resistance as well as indices of adiposity such as BMI, abdominal fat areas, and adipocyte size in fat depots." (PMID 27465988, 2016).
kidney damage (2 papers, 2020 to 2022). "Although the IRI nephropathy model is different from the aldosterone/salt model, these studies showed a significant role for increased biglycan expression in the progression of kidney injury." (PMID 35743123, 2022).
lung fibrosis (2 papers, 2010 to 2024). "Lower decorin and higher biglycan levels correlate with increased disease severity, emphasizing their potential to identify patients at risk for lung fibrosis and guide clinical management." (PMID 39906348, 2024). "Surprisingly, these data are consistent with a rat model investigating bleomycin-induced pulmonary fibrosis, which showed that biglycan production was increased early in the fibrotic process and declined over time, while decorin production was enhanced later in this process." (PMID 20459817, 2010).
male infertility (2 papers, 2016 to 2022). The inability of the male to effect fertilization of an ovum after a specified period of unprotected intercourse. "ECM is present between the layers of peritubular cells in the human testis, normally, and its composition and ECM amounts change in idiopathic male infertility when, for example, the DCN and BGN levels increase." (PMID 36429113, 2022).
metastatic diseases (2 papers, 2018 to 2021). "We found that biglycan, a small leucine-rich repeat proteoglycan, was one of the molecules responsible for these phenotypes in metastatic tumor TECs." (PMID 29695087, 2018). "Furthermore, the biglycan promoter was markedly demethylated in TECs from metastatic tumors, but not in other ECs, and this demethylation shows that epigenetic dysregulation might be one of the mechanisms involved in TEC abnormalities." (PMID 29695087, 2018).
muscular dystrophies (2 papers, 2012). "The potential of biglycan asa novel therapeutic target or agent for the treatment of inflammatory diseases andskeletal muscular dystrophies is also addressed." (PMID 22821552, 2012). "Furthermore, the biglycan knockout mouse displays mild muscular dystrophy." (PMID 22253749, 2012).
oral cancer (2 papers, 2022 to 2023). "BGN has been shown to localize in differentiating keratinocytes, scarring and oral cancer, and the BGN in OMK-ECM can undergo degradation during inflammatory processes." (PMID 36968250, 2023). "A panel of five genes (MMP1, FBLN5, COL5A3, BGN and LOXL1) was useful for predication the successful grafters among oral cancer patients." (PMID 35444950, 2022).
osteogenesis imperfecta (2 papers, 2016 to 2020). Osteogenesis imperfecta (OI) comprises a heterogeneous group of genetic disorders characterized by increased bone fragility, low bone mass, and susceptibility to bone fractures with variable severity. "The changes in collagen fibrils in an osteogenesis imperfecta model and the double gene deletion of decorin and biglycan were structural because these proteins were involved in either the conformational changes of the collagen subunit or the knitting of collagen fibrils." (PMID 31988398, 2020).
periodontal disease (2 papers, 2008 to 2021). "ECM degradation is a key event in the early stages of periodontal disease, generating fragments that can act as danger-associated molecular patterns (DAMPs) such as fragmented aggrecan, fibronectin, biglycan, decorin and low molecular weight hyaluronic acid." (PMID 34255809, 2021). "The influence of LPS on the synthesis of matrix proteins, such as biglycan and decorin, therefore presents one, albeit significant, consequence of the pathogenic action of P. gingivalis in the progression of periodontal disease." (PMID 18471238, 2008). "Raised levels of decorin and biglycan in the gingival crevicular fluid (GCF) have been proposed as potential markers of alveolar bone destruction, during periodontal disease and peri-implantitis." (PMID 18471238, 2008).
retinal detachment (2 papers, 2021 to 2022). An eye emergency condition which may lead to blindness if left untreated. "After retinal detachment, there was a significant increase in biglycan gene expression after seven days of retinal detachment." (PMID 35269741, 2022). "Discordant to previous findings, a study investigating kainic acid-induced retinal detachment found weak biglycan staining patterns for both normal and detached retinas, suggesting that biglycan may have a limited or insignificant role in retinal repair." (PMID 34298915, 2021).
Turner syndrome (2 papers, 2012 to 2021). Turner syndrome is a chromosomal disorder associated with the complete or partial absence of an X chromosome. "Furthermore, BGN is reduced in individuals with Turner syndrome—a condition that affects only females, where one of the X chromosomes is missing or partially missing—who suffer from vascular anomalies including aortic dissection and rupture." (PMID 33413676, 2021). "A role for biglycan in the growth of bone was suspected based on the observation thatfemale patients with Turner syndrome, lacking the second X chromosome, have a shorterstature and abnormally low expression of biglycan, contrary to patients with supernumerary Xchromosomes." (PMID 22821552, 2012).
aging (1 paper, 2021). A developmental process that is a deterioration and loss of function over time. "Thus, it is considered that degrading enzymes of biglycan and decorin can promote skin aging, and this study newly suggests possible roles of ADAMTS5 as a degrading enzyme of biglycan and decorin." (PMID 33573338, 2021).
amoebiasis (1 paper, 2022). "The prime module in protein-protein interaction network of DEGs, including ADAMTS2, COL10A1, COL1A1, COL1A2, COL8A1, BGN, and SPP1, was enriched in protein digestion and absorption, ECM-receptor interaction, focal adhesion, PI3K-Akt signaling pathway, and amoebiasis." (PMID 35726219, 2022).
Aortic dissection (1 paper, 2016). Aortic dissection refers to a tear in the intimal layer of the aorta causing a separation between the intima and the medial layers of the aorta. "While the results do not remain significant after adjustment for multiple tests, CNVs involving BGN may contribute to TAAD, because deletion of BGN in mice causes thoracic aortic dissections." (PMID 27092555, 2016).
Arterial thrombosis (1 paper, 2021). The formation of a blood clot inside an artery. "However, the impact of small proteoglycans as ECM proteins of the vessel wall—especially of biglycan—in platelet adhesion and activation in hemostasis and arterial thrombosis is poorly understood." (PMID 34830059, 2021).
Atrophy (1 paper, 2025). Any weakening or degeneration, especially through lack of use. "Muscle atrophy is defined as a decline in muscle mass and function and is closely correlated with aging; thus, we next examined the effect of BGN on muscle atrophy." (PMID 40943208, 2025). "Given that aging-related muscle atrophy results from increased muscle protein breakdown and decreased synthesis of new proteins, we hypothesized that BGN promotes protein synthesis." (PMID 40943208, 2025).
B-cell non-Hodgkin lymphoma (1 paper, 2022). The most common type of non-Hodgkin lymphoma. "Interestingly, a subset of the members in the SLRP protein family have been previously identified in B-cell Non-Hodgkin’s lymphomas including DCN, BGN, ASPN, FMOD, LUM, PRELP, and TSKU." (PMID 36873459, 2022).
basal cell carcinoma (1 paper, 2023). A carcinoma involving the basal cells. "In addition, malignant cells in basal cell carcinoma also expressed a medium level of BGN." (PMID 36772945, 2023).
bladder tumor (1 paper, 2020). "Studies have revealed that the expression of Biglycan (BGN) is related to high grade human bladder tumor, and a series of experiments have proved that BGN is an inhibitor of bladder tumor cell growth and proliferation." (PMID 32596162, 2020).
Cirrhosis (1 paper, 2016). A chronic disorder of the liver in which liver tissue becomes scarred and is partially replaced by regenerative nodules and fibrotic tissue resulting in loss of liver function. "Proteoglycan expression revealed the up-regulation of LUM and PRG2, while the abundance levels of BGN, that showed a gradual decrease during fibrosis progression, were found underexpressed up to 12 times in cirrhosis." (PMID 26998606, 2016).
colorectal tumors (1 paper, 2024). "Studies have shown that increased biglycan levels are associated with enhanced proliferation, motility, tumorigenesis, and liver metastasis of colorectal tumors." (PMID 38389090, 2024).
Corneal opacity (1 paper, 2013). A reduction of corneal clarity. "On the other hand under the influence of TGF beta these cells transform into myofibroblasts and produce high levels of other ECM components ie collagen, hyaluronan, and biglycan but low levels of keratin sulfate proteogylcans which results into a disorganized ECM and leads to corneal opacity." (PMID 23940587, 2013).
dyslipidemia (1 paper, 2019). "Moreover, dyslipidemia contributes to an increase in several endogenous ligands for TLR4 including hyaluronic acid, biglycan and oxidized LDL." (PMID 30530865, 2019).
Ehlers-Danlos Syndrome type IV (1 paper, 2022). "With regards to collagen integrity, deficiencies in the following proteins are relevant: biglycan (an ECM component regulating collagen formation) and collagen 3 α1 chain (implied in Ehlers-Danlos Syndrome type IV)." (PMID 35224059, 2022).
endometrial tumors (1 paper, 2025). "In addition, PGs such as decorin and biglycan—both implicated in fibril formation and matrix organization of endometrial tumors—may also serve as future therapeutic targets or modulators of disease progression." (PMID 41228294, 2025).
fetal growth restriction (1 paper, 2023). A fetus that does not grow beyond the 10th percentile of conventionally accepted weight for gestational age. "The role of biglycan in thrombosis has not been investigated in detail, however, several studies indicate a potential regulatory role, with a reduction in biglycan associated with increased thrombotic risk in fetal growth restriction and increased platelet activation in mice." (PMID 37511615, 2023).
gastric adenocarcinoma (1 paper, 2022). "Furthermore, BGN, a key member of the small leucine-rich proteoglycan family, has been shown to participate in many cancers and is associated with poor prognosis in cancer patients, including gastric adenocarcinoma." (PMID 35726219, 2022). "Altogether, our bioinformatics analysis study identified six upregulated DEGs (ADAMTS2, COL10A1, COL1A1, COL1A2, COL8A1, and BGN) between gastric adenocarcinoma and normal tissues based on four different microarray datasets." (PMID 35726219, 2022).
glomerular diseases (1 paper, 2009). "Minimal expression of biglycan in the mesangial matrix has been described for normal human kidney and various glomerular diseases." (PMID 19543532, 2009). "Biglycan is not detectable in the urine of patients with glomerular diseases." (PMID 19543532, 2009).
Granuloma (1 paper, 2019). A compact, organized collection of mature mononuclear phagocytes, which may be but is not necessarily accompanied by accessory features such as necrosis. "In mice with surgical sponge-induced granulomas, and in atherosclerotic plaques, a variety of genes associated with fibrosis are expressed in transcriptome analysis: several collagen peptides and the small proteoglycans decorin and biglycan." (PMID 31736973, 2019).
Helicobacter pylori (1 paper, 2022). "BGN expression showed a significant correlation with histologic grade, histologic type, histologic stage, T stage, and Helicobacter pylori (HP) infection in patients with GC." (PMID 35154268, 2022).
Infertility (1 paper, 2016). "We conclude that TLR2 and BGN contribute to sterile inflammation and infertility in man." (PMID 27849015, 2016). "To examine whether BGN levels also vary in vivo, we used immunohistochemistry for testicular samples from normal and infertility patients, namely mixed atrophy patients, in which normal and impaired spermatogenesis co-exist." (PMID 27849015, 2016). "Thus, testicular macrophage-derived BGN may be a further player in infertility, as well." (PMID 27849015, 2016).
juvenile idiopathic arthritis (1 paper, 2025). Juvenile idiopathic arthritis (JIA) is the term used to describe a group of inflammatory articular disorders of unknown cause that begin before the age of 16 and last over 6 weeks. "Therefore, our study aimed to evaluate the diagnostic utility of plasma proteoglycan profiles, namely, aggrecan, decorin, and biglycan, released from osteoarticular structures into the blood of children with juvenile idiopathic arthritis." (PMID 41465591, 2025).
kidney injury (1 paper, 2022). Trauma to the kidney. "In conclusion, this study identifies biglycan as a possible novel target modulated by an MRA in glomeruli upon NAS-induced kidney injury." (PMID 35743123, 2022).
lobular carcinomas (1 paper, 2007). "Several genes encoding proteins involved in actin, calcium and metal ion binding were downregulated (MYBPC1, DST, PIP, CA2), and some genes with the same function (BGN, ADAM12) were upregulated in lobular carcinomas." (PMID 17389037, 2007).
lung adenocarcinoma (1 paper, 2021). A carcinoma that arises from the lung and is characterized by the presence of malignant glandular epithelial cells. "Oncomine database indicated that the expression of BGN was higher in 226 lung adenocarcinoma compared to that in 20 normal lung tissue samples." (PMID 33709550, 2021).
lymphangioleiomyomatosis (1 paper, 2008). A multifocal neoplasm with perivascular epithelioid cell differentiation affecting almost exclusively females of child-bearing age. "In lymphangioleiomyomatosis (LAM), thickened alveolar walls and expanded interstitial tissues stain strongly for versican, as well as biglycan." (PMID 18485243, 2008).
mesenchymal tumors (1 paper, 2018). "Biglycan, an important component of bone ECM, has been correlated to the emergence of mesenchymal tumors." (PMID 30406034, 2018).
metastasis (1 paper, 2023). The spread or migration of cancer cells from one part of the body (where they first appeared) to another. "High BGN expression was notably associated with tumor size, tumor invasion, and lymph node metastasis (p < 0.05 for all) of patients with ESCC." (PMID 35789548, 2023).